RHBDL3 (rhomboid like 3)
Description:
May be involved in regulated intramembrane proteolysis and the subsequent release of functional polypeptides from their membrane anchors.
Synonyms: RHBDL4; VRHO
Tractability: Antibody: UniProt predicts a signal peptide or a membrane-spanning region.
Gene: Protein-coding gene on chromosome 17 (32,265,787 to 32,324,663, forward strand). Ensembl gene ENSG00000141314.
Subcellular location: Membrane
Gene Ontology:
Molecular function: serine-type endopeptidase activity; calcium ion binding
Cellular component: membrane
Genetic constraint (gnomAD): Loss-of-function variants: 20 observed, 37.02 expected, observed/expected ratio (o/e) 0.54, 90% interval 0.38 to 0.79. The upper end of that interval is the gene's LOEUF score, 0.79, which puts it in group 3 of 6, group 1 being the genes least tolerant of losing a copy. Missense variants: 417 observed, 484.27 expected, observed/expected ratio (o/e) 0.86, 90% interval 0.79 to 0.93. Synonymous variants: 186 observed, 211.47 expected, observed/expected ratio (o/e) 0.88, 90% interval 0.78 to 0.99.
Homologues: Orthologues: macaque RHBDL3 (99% identical), dog RHBDL3 (98% identical), pig RHBDL3 (97% identical), rat Rhbdl3 (96% identical), mouse Rhbdl3 (96% identical), guinea pig RHBDL3 (87% identical), rabbit RHBDL3 (75% identical), zebrafish rhbdl3 (73% identical), chimpanzee RHBDL3 (69% identical), tropical clawed frog RHBDL3 (68% identical), Drosophila melanogaster stet (28% identical), Drosophila melanogaster rho-5 (24% identical), and 6 more. Paralogues in human: RHBDL1 (52% identical), RHBDL2 (26% identical), RHBDF1 (23% identical), RHBDF2 (21% identical), PARL (14% identical).
Diseases named in the same sentence as RHBDL3 in open-access papers:
RHBDL3 is named in the same sentence as 2 diseases in open-access papers, as found by Europe PMC text mining. Sharing a sentence is not in itself a finding about the gene and the disease. The quoted sentences say what the papers report.
cancer (1 paper, 2024). A tumor composed of atypical neoplastic, often pleomorphic cells that invade other tissues. "Moreover, the variant on BTA19 at 17,893,592 bp that affects MY and MAS, in our study, is located nearby the RHBDL3 gene, which was mentioned to have an influence on a wide range of human diseases like cancer or inflammatory diseases." (PMID 38589805, 2024).
psychiatric disease (1 paper, 2024). "Within our dataset, genes with shifted aging trajectories in psychiatric disease include APLF (in Exc_L2–L3, Exc_L4–L6_1 and Exc_L4–L6_2 neurons), EXPH5 (in Exc_L2–L3 and Exc_L4–L6_3 neurons) and RHBDL3 (in Exc_L4–L6_2 neurons)." (PMID 39227716, 2024).